RN7SL494P (RNA, 7SL, cytoplasmic 494, pseudogene)
Gene: Miscellaneous RNA gene on chromosome 15 (50,244,628 to 50,244,931, reverse strand). Ensembl gene ENSG00000241175.
Homologues: Orthologues: chimpanzee Metazoa_SRP (99% identical), macaque Metazoa_SRP (92% identical), rabbit Metazoa_SRP (67% identical), rat Metazoa_SRP (64% identical), guinea pig Metazoa_SRP (58% identical). Paralogues in human: RN7SL2 (76% identical), RN7SL1 (75% identical), RN7SL3 (73% identical), RN7SL4P (72% identical), RN7SL357P (72% identical), RN7SL47P (72% identical), RN7SL126P (71% identical), RN7SL14P (71% identical), RN7SL333P (71% identical), RN7SL33P (71% identical), RN7SL769P (71% identical), RN7SL147P (71% identical), and 698 more.
Diseases named in the same sentence as RN7SL494P in open-access papers:
RN7SL494P is named in the same sentence as 3 diseases in open-access papers, as found by Europe PMC text mining. Sharing a sentence is not in itself a finding about the gene and the disease. The quoted sentences say what the papers report.
lung adenocarcinoma (1 paper, 2019). A carcinoma that arises from the lung and is characterized by the presence of malignant glandular epithelial cells. "We conducted GO analysis for all the differentially expressed genes in the lung adenocarcinoma cases in the current study and found that the gene RN7SL494P was not involved in any biological functions or processes in the DAVID database, nor was it related to any cellular components of the database." (PMID 31827762, 2019).
tumor (1 paper, 2019). "We speculate that the gene RN7SL494P may exhibit “inconsistent functions” in different tumor microenvironments." (PMID 31827762, 2019).
RN7SL494P also shares sentences with these, for which no sentence is quoted: cancer (1 paper).